INS (insulin)
Diseases named in the same sentence as INS in open-access papers (continued):
Sharing a sentence is not in itself a finding about the gene and the disease.
Hypoglycemia (continued). "The Zip14−/− phenotype included greater body fat, hypoglycemia and higher insulin levels, as well as increased liver glucose and greater phosphorylation of the insulin receptor and increased GLUT2, SREBP-1c and FASN expression." (PMID 23110240, 2012). "Discussion of the methods for testing of the accuracy and the utility of such alarms has been initiated, and the next logical step—prevention of hypoglycemia via shutoff of the insulin pump—has been undertaken." (PMID 24278682, 2012). "In the training group two patients needed to reduce their insulin and one to take away the oral antidiabetics due to hypoglycaemia." (PMID 22593770, 2012). "In particular, B6 (excitotoxin cell death resistant) mice with insulin-induced hypoglycemia following by KA-induced SE exhibited greater seizure-induced cell death." (PMID 22867059, 2012). "Despite the daily burden of monitoring blood sugar, taking insulin, and experiencing episodic and occasionally severe hypoglycemia, T1D patients can enjoy a relatively healthy life for decades." (PMID 22807927, 2012). "The effect of insulin-induced hypoglycemia to induce changes in glycogen levels in retina was also examined." (PMID 22363495, 2012). "The rate of hypoglycemia was highest in those on insulin alone in both groups, averaging about 6 episodes for every 100 person-years in the intensive group and almost 3 episodes per 100 person-years in the standard group." (PMID 22646230, 2012). "In studies later conducted with the same sensor at the University of Perugia, similar performance was observed during insulin-induced hypoglycemia and subsequent phases." (PMID 23202020, 2012). "Sik3−/− mice have a malnourished the phenotype (i.e., lipodystrophy, hypolipidemia, hypoglycemia, and hyper-insulin sensitivity) accompanied by cholestasis and cholelithiasis." (PMID 22662228, 2012). "We therefore initiated prandial aspart insulin, hoping to blunt the postprandial glucose peak and excessive insulin surge and thus prevent the resultant hypoglycemia." (PMID 22937294, 2012). "Emergency Department physicians must be aware of the possibility of insulin overdose in any patient presenting with hypoglycaemia." (PMID 22924049, 2012). "Due to poor appetite and hypoglycemia, the patient omitted her insulin dose at lunch time; the same evening, she felt worse and was brought to our emergency department by her parents." (PMID 22394704, 2012). "On the other hand, insulin sensitisers (glitazones) and incretin based therapies (DPP-4 inhibitors, GLP-1 analogues) have been associated with a low risk of hypoglycaemia." (PMID 23075070, 2012). "During insulin-induced hypoglycemia, glucagon raises blood glucose levels by enhancing glycogenolysis and gluconeogenesis to restore normoglycemia." (PMID 23316165, 2012). "The proportion of patients treated with intensive insulin who developed hypoglycemia varied greatly between studies, ranging from 3 to 100%, with a median value of 18 to 33%." (PMID 23082798, 2012). "Our data confirms previous studies showing that hypoglycemia (induced by bolus insulin administration) significantly modulated glucose levels." (PMID 22867059, 2012). "Studies have shown that use of automated bolus advisor technology among insulin pump users facilitates accurate determination of prandial insulin dosages, reduces postprandial excursion, and reduces hypoglycaemia, leading to improved glycaemic control." (PMID 23062116, 2012). "Combined treatment with losartan and PD123319 proved to be more effective in attenuating the reflex increase in plasma adrenaline concentrations during insulin-induced hypoglycemia than either of the two Ang II receptor antagonists given alone." (PMID 22558183, 2012). "The two clinical variables, i.e. HbA1c values and insulin treatment were the only significant predictors of increased perceived hyper- and hypoglycaemia, with the regression models explaining 23.2% and 26.8% of the variance respectively." (PMID 22296783, 2012).
Hypoglycemia (continued). "Patients and their physicians must be made aware of any changes that are instituted in their medications and insulin dosages postoperatively to avoid any adverse events, especially severe hypoglycemia." (PMID 23209941, 2012). "We studied her insulin secretion and blood glucose dynamics and were able to tailor a therapeutic regimen involving insulin that eliminated episodes of hypoglycemia.Methods." (PMID 22937294, 2012). "Long-acting insulin analogues have been shown to provide consistent glycaemic control with a lower incidence of hypoglycaemia compared with conventional insulin treatment with neutral protamine Hagedorn (NPH) insulin." (PMID 22340448, 2012). "Pancreatic insulinoma is characterized by fasting hypoglycemia with high plasma or serum concentration of insulin and C-peptide or proinsulin." (PMID 24213321, 2012). "In order to avoid this problem, diabetic rats were injected for 3 days with insulin, in order to avoid further effect of antecedent hypoglycemia." (PMID 22969729, 2012). "Blood glucose control using model-based methods has been applied successfully in limited adult clinical trials and large-scale clinical implementation, which reduced both blood glucose levels and hypoglycemia using a combined insulin and nutrition protocol." (PMID 22871230, 2012). "Among these, 71 (40.6%) hypoglycemic events occurred spontaneously and 104 (59.4%) occurred with insulin therapy (that is, iatrogenic hypoglycemia)." (PMID 23062226, 2012). "In a few cases, deviations were also a direct response to patients' resistance or refusal to have their insulin doses increased after experiencing severe hypoglycaemia." (PMID 21542916, 2011). "Patients on 0/1 OAD at baseline had significantly less symptomatic hypoglycaemia when basal insulin was added than those on 2 OADs (p = 0.0007)." (PMID 21481127, 2011). "While 2DG-induced glucoprivation is a useful experimental model of hypoglycemia, it does not precisely mimic the clinically relevant stimulus experienced by diabetic patients; namely insulin-induced hypoglycemia." (PMID 22162752, 2011). "In univariate analyses adjusted for gender, minutes spent in hypoglycemia were significantly correlated with age (r = 0.26; P = 0.01), waist circumference (r = 0.33; P = 0.003), 2-h glucose (r = 0.58; P<0.0001), and 2-h insulin (r = 0.27; P = 0.02)." (PMID 22164268, 2011). "Given the complicated nature of the euglycemic hyperinsulinemic clamp technique and the potential dangers of hypoglycemia in some patients, alternatives have been sought to simplify the measurement of insulin resistance." (PMID 21251282, 2011). "One event of major hypoglycaemia (liraglutide 1.8 mg group) occurred after regular insulin was infused as part of a substudy procedure." (PMID 21205128, 2011). "Patients on MET only at baseline also had the lowest rate of symptomatic and severe hypoglycaemia and the lowest weight gain after 24 weeks of treatment with insulin glargine in spite of a higher insulin dose on average." (PMID 21481127, 2011). "Surprisingly there was a significantly higher degree of insulin use in patients with anamnestic hypoglycaemia (OR 1.88; 95%CI 1.49-2.39), while less oral antidiabetic drugs were prescribed in these patients (mean 1.5 ± 0.7 vs. 1.8 ± 0.7; p < 0.0001)." (PMID 21756359, 2011). "Patients who regained insulin independence and hypoglycemia awareness after transplantation, but who had to eventually return to insulin, still kept the level of QoL above that experienced pre-transplantation." (PMID 25013604, 2011). "- Inappropriate plasma insulin levels (plasma insulin concentration detectable) and c-peptide concomitant to hypoglycemia." (PMID 21967988, 2011). "Several systems identified incidents of hypoglycaemia and detected high and low glucose levels as well as insulin dose changes, exercise and event marker entries." (PMID 21210964, 2011).
Hypoglycemia (continued). "In one recent study, most hospital hypoglycemia occurred in the early morning, which suggests the basal insulin dose was too high and perhaps the providers were reluctant to use fast-acting insulin analogs during the day." (PMID 23882328, 2011). "BAD is also required for proper counterregulatory responses to insulin-induced hypoglycemia as evident from significantly higher glucose infusion rates and lower plasma epinephrine levels during hyperinsulinemic hypoglycemic clamps." (PMID 22162752, 2011). "To investigate whole-body insulin sensitivity in a more physiological context (avoiding counterregulatory responses induced by hypoglycemia in insulin tolerance tests), we carried out a hyperinsulinemic-euglycemic clamp study." (PMID 21195350, 2011). "To test effects of hypoglycemia, we performed a 5-hour hyperinsulinemic/hypoglycemic clamp; to exclude an effect of insulin, we made a hyperinsulinemic/euglycemic clamp as control." (PMID 21738719, 2011). "In particular, the role of exogenous insulin, physiologic hormonal responses to hypoglycemia or ascorbic acid in inducing WAT glycolytic activity is uncertain." (PMID 22214514, 2011). "This approach was then tested overnight in young people, in whom hypoglycemia was induced by gradually increasing the subcutaneous insulin delivery." (PMID 22071283, 2011). "The clinical history was highly suggestive of an organic hypoglycemia, with normal or relatively low insulin concentrations and elevated proinsulin levels." (PMID 21765847, 2011). "Earlier, in the international community of islet transplantation, there was an agreement in that the primary aim of islet transplantation was to achieve insulin independency and secondly to regain hypoglycemia awareness." (PMID 25013604, 2011). "Weight gain can be a concern when children are on intensified insulin regimens or have frequent hypoglycemia." (PMID 22067102, 2011). "We showed herein for the first time that acute insulin-induced hypoglycemia led to retinal cell death via an activation of caspase 3 pathway and a decrease of GSH content." (PMID 21738719, 2011). "al. reported a utility decrement of 0.047 (p = 0.120) for patients experiencing any hypoglycemia in the preceding month, after adjusting for gender, insulin use, and hypoglycemia group (symptomatic, mild or severe)." (PMID 21777428, 2011). "- Inappropriately low ketone bodies in plasma and urines and low free fatty acids in plasma even for fasting hypoglycemia (Insulin inhibits lipolysis)." (PMID 21967988, 2011). "Among these, 10 and 15 subjects, respectively, experienced an episode of hypoglycaemia 3–6 h after the insulin administration." (PMID 21205115, 2011). "In univariate analyses adjusted for gender and age, carotid IMT was significantly correlated with systolic and diastolic blood pressure, total and LDL cholesterol, 2-h post-load plasma glucose, insulin sensitivity, and minutes spent in hypoglycemia." (PMID 22164268, 2011). "Our work with Tomosyn-2 provides new insights into the regulation of insulin secretion and emphasizes that negative regulation is critical for avoiding insulin-induced hypoglycemia." (PMID 21998599, 2011). "A glucose infusion rate higher than 10 mg/kg.min in a neonate proves an insulin related hypoglycemia." (PMID 21967988, 2011). "Significant hypoglycaemia is however unlikely given the glucose bolus administered concurrently with insulin." (PMID 21541209, 2011). "The use of BreathID® continuous online 13C-Octanoic acid breath test system for the detection of the relationship between hypoglycemia and gastric emptying abnormalities in diabetic patients treated with subcutaneous insulin has been already published as well." (PMID 21929798, 2011). "The relevance of BAD in this adaptive response is apparent in two different models of systemic hypoglycemia; 2DG-induced glucoprivation and the more clinically relevant paradigm of insulin-induced hypoglycemia." (PMID 22162752, 2011).
Hypoglycemia (continued). "The risks increased in older patients, coexisting severe comorbidities, the presence of undiagnosed hypoglycemia, and the duration of diabetes and insulin therapy." (PMID 22242020, 2011). "Accordingly, it is likely the patient was euglycemic on arrival and was administered FDG during a period of insulin-induced hypoglycemia." (PMID 22214514, 2011). "We showed, for the first time, that acute insulin-induced hypoglycemia leads to caspase 3-dependant retinal cell death with a predominant role of GSH content." (PMID 21738719, 2011). "Our results reveal that one subgroup includes the patients that have regained insulin independency and hypoglycemia awareness." (PMID 25013604, 2011). "In our study, nearly 70% of people taking insulin tested their blood glucose, with over half reporting hypoglycaemia." (PMID 21166853, 2011). "The other subgroup consists of patients that have regained insulin independency and hypoglycemia awareness but had to return to insulin again." (PMID 25013604, 2011). "There was a higher proportion of infants with neonatal hypoglycemia in the insulin group (8.1%) compared with the metformin group (3.3%) (P-value: 0.008)." (PMID 21501437, 2011). "More predictable glycaemic-lowering profiles of the insulin analogues have also led to reductions in nocturnal hypoglycaemia, particularly comparing long-acting insulin analogues with protaminated human insulin." (PMID 21410860, 2011). "We showed that acute insulin-induced hypoglycemia in mouse (blood glucose at 2.2 mM) led to retinal apoptosis through the activation of caspase 3 and the modulation of retinal GSH content." (PMID 21738719, 2011). "Patient fears regarding possible adverse health consequences associated with intensifying insulin therapy, such as weight gain or hypoglycemia, also factor into adherence to a treatment regimen including mealtime insulin." (PMID 21226935, 2011). "And, the Sirt6 knockout mice showed severe hypoglycemia by enhancing insulin signaling and subsequent glucose uptake." (PMID 21373642, 2011). "The theoretical benefits of decreased nocturnal hypoglycemia and twice daily insulin injection times was very attractive to families; particularly those that struggle with compliance." (PMID 22067102, 2011). "In the medical ICU trial the markedly higher rate of severe hypoglycemia in patients attenuated the beneficial impact of intensive insulin therapy observed in the surgical ICU trial." (PMID 21787410, 2011). "The detrimental effects of insulin therapy, such as hypoglycemia leading to stroke, was more evident in the elderly in the present study." (PMID 21978180, 2011). "Hypoglycemia treatment is clearly addressed in the glycemic protocol and if any untoward events or side effects of insulin are noted, the endocrinology fellow is consulted immediately." (PMID 21912542, 2011). "Long-term resistance to hypoglycemia would allow for more aggressive insulin regimens for patients, providing improved patient outcomes while reducing the incidence of adverse effects." (PMID 20418955, 2010). "One of the key patient barriers is fear of hypoglycaemia, which can be managed by appropriate training, introduction of blood glucose self-monitoring, use of basal insulin analogues and translation of PD concepts into practical clinical dosing regimens." (PMID 20618882, 2010). "According to the ADOPT study, patients on insulin sensitizers (metformin or rosiglitazone) experienced hypoglycemia at a rate of about 10% over 5 years of treatment." (PMID 20723229, 2010). "Sometimes, hypoglycemia was accompanied by increased plasma insulin concentrations as compared to wild type mice." (PMID 20936117, 2010). "It has been reported that insulin-induced hypoglycemia affects repolarization of the cardiac cells in both healthy subjects and people with diabetes." (PMID 21234404, 2010).
Hypoglycemia (continued). "MODY2, for example, exhibited relatively uniform dynamics for all simulations, with consistent early onset but mild hypoglycemia (indicated by moderately low insulin level)." (PMID 20587063, 2010). "Efficacy of the construct was assessed in beagle dogs using an insulin challenge to induce hypoglycemia." (PMID 20418955, 2010). "Althoughrecovery from insulin-induced hypoglycemia was impaired in C57BL/6J ClockΔ19 mutantand Bmal1-/- knockout mice, the counter-regulatory responsesof corticosterone and glucagon were retained." (PMID 20228939, 2010). "In the insulin trial, five patients (3.4%) treated with colesevelam and eight patients (6.0%) treated with placebo reported hypoglycaemia that was considered to be drug-related." (PMID 20415686, 2010). "The exenatide groups exhibited weight loss as opposed to weight gain and improved postprandial glucose control compared with either insulin group, and less nocturnal hypoglycemia compared with insulin glargine." (PMID 27713388, 2010). "Hypoglycemia was reached 45 ± 32 minutes after insulin was administered with blood glucose at nadir of 2.4 ± 0.3 mmol/L." (PMID 21234404, 2010). "Lately, there is a tendency for early initiation of insulin administration but unfortunately, this strategy is held back by the fear of hypoglycaemia, weight gain, and injections." (PMID 20589066, 2010). "Administration of insulin (daily) is inconvenient; hypoglycemia and wt gain are its known adverse effects." (PMID 20582183, 2010). "Ideally, results from glucose-clamp studies on basal insulin analogues should be applicable in the clinic when one wants to determine the optimal balance between metabolic control and hypoglycaemia." (PMID 20618882, 2010). "In general, improvements in blood glucose control can only be judged in the context of hypoglycaemia incidence as well as insulin dose." (PMID 20946269, 2010). "Other possible outputs are recommendations concerning insulin boli, food intake, monitoring interval, hypoglycemia correction, and so on." (PMID 20840773, 2010). "The increase in weight in patients treated with insulin secretagogues (sulfonylureas and repaglinide or nateglinide) and insulin results mostly from improved glycaemic control and increases in caloric intake as a result of hypoglycaemia." (PMID 20671994, 2010). "The need for optimal efficacy (reaching target values and minimizing variations) and for maximum safety (reducing the incidence of hypoglycemia) is nevertheless a strong argument in favor of continuous intravenous insulin infusion by an electric syringe pump." (PMID 20840773, 2010). "The observed side effect profile consisted mainly of mild to moderate nausea, and rates of hypoglycemia were comparable to that of placebo (when combined with metformin) and to insulin comparator (when combined with metformin & SU)." (PMID 27713366, 2010). "The late postprandial dumping syndrome accompanying gastrectomy is characterized by hypoglycemia principally due to excessive insulin release." (PMID 20721337, 2010). "Data evaluation considered the weighted mean difference and odds ratio for insulin dose, birth weight, gestational age, delivery mode, hypoglycemic episodes, worsening retinopathy, neonatal hypoglycemia, and rates of intrauterine fetal death." (PMID 20589066, 2010). "These barriers include reaching glycaemic goals, overcoming the reality and fear of hypoglycaemia, and appropriate insulin therapy and dose adjustment." (PMID 20456170, 2010). "Parents of children receiving insulin injections scored higher than parents of children using CSII on the behaviour subscale (P =< 0.001) but for all parents, severe hypoglycaemia in a child is one of the most important causes of fear." (PMID 20633252, 2010).